PIEZO1 (piezo type mechanosensitive ion channel component 1 (Er blood group))
Diseases named in the same sentence as PIEZO1 in open-access papers (continued):
Sharing a sentence is not in itself a finding about the gene and the disease.
renal fibrosis (18 papers, 2021 to 2025). A final common manifestation of a wide variety of chronic kidney diseases characterized by glomerulosclerosis and tubulointerstitial fibrosis. "Piezo1 has been implicated in various fibrotic diseases, including pulmonary and renal fibrosis, through pathways involving TGF-β/SMAD or P38/MAPK." (PMID 39000341, 2024). "Piezo1 inhibition partially prevented renal fibrosis caused by UUO or folic acid treatment." (PMID 38338996, 2024). "In addition, the use of Piezo1 inhibitor GsMTx4 can significantly improve the degree of renal fibrosis caused by the unilateral ureter." (PMID 38362490, 2024). "It is recognized that mechanical stimulus is closely associated with kidney fibrosis; whether Piezo1 as a candidate mechanosensor is involved in progression of renal fibrosis is still unknown." (PMID 35230979, 2022). "Renal fibrosis is associated with increased Piezo1 protein expression." (PMID 35230979, 2022). "The involvement of Piezo1 in the process of renal fibrosis was confirmed by experiments with the application of Yoda1." (PMID 38338996, 2024). "This strongly suggests that Piezo1 plays an important role in UUTD caused by ureteral obstruction and the development of renal fibrosis." (PMID 38362490, 2024). "During research carried out on mice, inhibition of Piezo1 channels by GsMTx4 and Piezo1 siRNA, as well as Piezo1 gene knockout, resulted in a significant reduction in renal fibrosis." (PMID 38338996, 2024). "In conclusion, we found Piezo1 promoted the initiation and development of renal fibrosis and inhibiting Piezo1 improved the fibrosis." (PMID 39496543, 2024). "Piezo1 can activate the CCL2-CCR2 pathway via Notch, causing macrophage aggregation to trigger inflammation and thereby mediating ECM deposition and renal fibrosis." (PMID 37900917, 2023). "Nevertheless, inhibition of Piezo1 by GsMTx4, at least, partially, contributes to attenuation of kidney fibrosis, and activation of Piezo1 was involved in the development of renal fibrosis." (PMID 35230979, 2022). "The CCL2-dependent recruitment of macrophages to the nerve injury site is most likely initiated by the mechanically activated cationic channel Piezo1, as it was suggested for macrophages involved in renal fibrosis." (PMID 36293246, 2022). "We demonstrated that inhibition of Piezo1 at least partially prevented unilateral ureter obstruction (UUO) or folic acid–induced renal fibrosis." (PMID 35230979, 2022). "Masson staining further demonstrated that renal fibrosis was alleviated in Piezo1 knockdown UUO mice." (PMID 34805150, 2021). "Altogether, these results indicated that Piezo1 knockdown alleviated renal fibrosis induced by UUO through p38MAPK-YAP pathway." (PMID 34805150, 2021). "Collectively, our results for the first time demonstrate enhanced matrix stiffness aggravates the progression of renal fibrosis through the Piezo1-p38MAPK-YAP pathway." (PMID 34805150, 2021). "To verify that Piezo1 knockdown alleviate renal fibrosis through the p38MAPK-YAP pathway, we examined the expression of p-p38, p38 and YAP expression in four groups." (PMID 34805150, 2021). "In a renal fibrosis model, GsMTx4 effectively attenuated the upregulation of Piezo1 in the kidney." (PMID 41332397, 2025). "Moreover, excessive deposition of ECM in turn increases Piezo1 expression and enhances the mechanosensory capacity, aggravating the progression of renal fibrosis." (PMID 40667648, 2025). "We assessed the expression of Piezo1 in the kidney to investigate whether Piezo1 was essential in renal fibrosis." (PMID 39496543, 2024). "Although Piezo1 is crucial in renal fibrosis, whether Piezo1 can induce or accelerate the renal fibrosis through facilitating mitochondrial dysfunction and the renal tubular epithelial cell apoptosis is unknown." (PMID 39496543, 2024). "In contrast, Zhao X found Yoda1 treatment caused renal fibrosis but did not affect the Piezo1 abundance." (PMID 39496543, 2024).
renal fibrosis (continued). "Similarly, inhibition Piezo1 with GsMTx4 also partly relieved the renal injury, renal fibrosis, apoptosis and mitochondrial dysfunction in vivo and vitro." (PMID 39496543, 2024). "Consequently, the aim of this study was to investigate the relationships among Piezo1, mitochondrial dysfunction, and apoptosis in the initiation and progression of kidney fibrosis and to explored a new mechanism for renal fibrosis." (PMID 39496543, 2024). "Recent research revealed that Piezo1 expressed markedly elevated in fibrotic kidneys, and treatment of the UUO model with GsMTx4, a blocker of Piezo1, revealed a significant attenuation of renal fibrosis, indicating that Piezo1 has an essential function in renal fibrosis." (PMID 37900917, 2023). "Upregulation of Piezo1 in renal fibrosis also occurs during fibrosis." (PMID 37900917, 2023). "It is worth mentioning that although TGF-β1 is an important marker of EMT, some studies have not found a strong correlation between EMT and renal fibrosis in vivo, indicating that Piezo1 may have a more complex role in renal fibrosis." (PMID 37900917, 2023). "Next, we investigated the potential molecular mechanisms by which Piezo1 mediates renal fibrosis." (PMID 35230979, 2022). "Our findings highlight the importance of external mechanical stress, mechanical sensors (Piezo1), and intracellular biological signaling pathways in the development of renal fibrosis, suggesting that blockade of the Piezo1 is probably a therapeutic option to delay the progress of kidney fibrosis." (PMID 35230979, 2022). "Targeting the Piezo1 pathway may offer a novel therapeutic strategy for ameliorating renal fibrosis." (PMID 35230979, 2022). "Targeting mechanosensitive Piezo1 might be a potential therapeutic strategy for delaying the progression of renal fibrosis." (PMID 34805150, 2021). "Moreover, we also found that a significant increase in Piezo1 expression in renal fibrosis induced by UUO." (PMID 34805150, 2021). "In addition, compared to the UUO group, Piezo1 knockdown UUO mice showed decreased levels of the renal fibrosis markers α-SMA, Collagen I and Fibronectin." (PMID 34805150, 2021). "In our study, we found that Piezo1 was expressed in the proximal tubules of UUO model mice and obstructed kidneys samples from humans, and that the abundance of Piezo1 mRNA and protein were positively associated with renal injury and renal fibrosis, this is consistent with previous reports." (PMID 39496543, 2024). "Similarly, many studies have investigated the relationships between Piezo1 and different types of fibrosis, such as pulmonary fibrosis, skin fibroproliferative disease, cardiac fibrosis, pancreatic fibrosis, and renal fibrosis." (PMID 39496543, 2024). "Moreover, a relevant Piezo1 role was also recently addressed in the regulation of renal fibrosis." (PMID 35897650, 2022). "Next, we investigated whether inhibition of Piezo1 improved UUO-induced renal fibrosis." (PMID 35230979, 2022). "Moreover, in vivo experiment showed that Piezo1 knockdown could alleviate renal fibrosis and renal function, and which the process mediated by the p38MAPK-YAP pathway." (PMID 34805150, 2021). "Furthermore, an animal model of renal fibrosis induced by unilateral ureteral obstruction (UUO) was used to observe the Piezo1-p38MAPK-YAP signaling pathway also plays a role in vivo and the intervention of Piezo1 can alleviate the progression of renal fibrosis." (PMID 34805150, 2021). "Moreover, the progression of renal fibrosis can be alleviated by intervening Piezo1." (PMID 34805150, 2021). "In renal fibrosis, a study reported that TGF‐β1 administration increased Piezo1 expression in proximal tubular cells." (PMID 39328029, 2024). "Mechanical stretch or Piezo1 activators can lead to an increase in intracellular calcium ions, increased expression of TGF-β1, and promote ECM synthesis and renal fibrosis." (PMID 37900917, 2023).
renal fibrosis (continued). "Lentiviral particles containing short hairpin RNA (sh RNA) targeting Piezo1 were used to explore the effect of Piezo1 knockdown on matrix stiffness-induced MCs activation and UUO-induced renal fibrosis." (PMID 34805150, 2021). "Interestingly, administration of a Piezo1 agonist (Yoda1) leads to increased TGF-β levels, contributing to fibrotic conditions such as renal fibrosis." (PMID 39000341, 2024). "In the unilateral ureteral obstruction (UUO) model, Piezo1 deletion was observed followed by a crucial reduction in the CCL2-CCR2 signaling pathway and Notch pathway, which inhibited the inflammation of macrophages and the progression of renal fibrosis." (PMID 37900917, 2023). "Piezo1 can increase macrophage accumulation by upregulating CCL2, the C-C motif chemokine receptor 2 (CCR2) pathway, and the knockout of Piezo1 in mice can inhibit macrophage infiltration, inflammation, and renal fibrosis." (PMID 37509528, 2023). "As GsMTx4 is not a specific inhibitor of Piezo1, the role of Piezo1 in renal fibrosis was further verified by using a Piezo1-specific agonist, Yoda1." (PMID 35230979, 2022). "When Piezo1 is activated, a large amount of calcium ions inward flow may activate the P38-MAPK molecule, and P38-MAPK reactivates YAP, and YAP induces ECM deposition and promotes the process of renal fibrosis." (PMID 37900917, 2023). "Furthermore, these consequences have been verified in the animal model of renal fibrosis induced by UUO and Piezo1 knockdown could alleviate UUO-induced fibrosis and improve renal function in vivo." (PMID 34805150, 2021). "Furthermore, PIEZO1-mediated Ca2+ influx is involved in inflammatory pathways including the IL-6 receptor family and Ca2+-sensitive MAPK family such as p38 in various systems (e.g., renal fibrosis models, liver carcinoma cell lines or human dermal fibroblasts)." (PMID 35406763, 2022). "However, it is not clear whether Piezo1 acts as an upstream mechanical response to YAP in renal fibrosis." (PMID 34805150, 2021).
Alzheimer disease (17 papers, 2018 to 2025). A progressive, neurodegenerative disease characterized by loss of function and death of nerve cells in several areas of the brain leading to loss of cognitive function such as memory and language. "Brain capillary ECs from mouse models of Alzheimer’s disease, cerebral small vessel disease, or Piezo1 gain-of-function mutation exhibited higher Piezo1 activity, that was corrected by exogenous ex vivo PIP2 application." (PMID 41433068, 2025). "Astrocytic Ca2+ activities were enhanced in a mouse model of Alzheimer’s disease, which was associated with increased expression of the Piezo1 channel." (PMID 37305437, 2023). "Similarly, it was observed that PIEZO1 expression is associated with Alzheimer’s disease pathogenesis and progression in the cerebellum (in vitro cerebellar cells) through DNAm." (PMID 40823415, 2025). "However, considering that PIEZO1 DNA hypomethylation has been associated with dysfunctional brain functioning, such as in Alzheimer’s disease, we expected that infants with NDs would exhibit lower PIEZO1 DNAm levels compared to infants with TD." (PMID 40823415, 2025). "For instance, fatty acids have been identified as modulators of Piezo1 in astrocytes, influencing cytokine release and gliosis in models of Alzheimer’s disease." (PMID 41009567, 2025). "This review will discuss microglial Piezo1 mechanosensitive channels as potential therapeutic targets for Alzheimer’s disease (AD)." (PMID 38957539, 2024). "Under pathological conditions, mechanical signals such as matrix stiffness‐mediated activation of Piezo1 are involved in regulating the development of brain aging, demyelinating diseases, Alzheimer's disease, brain tumors, and traumatic brain injury." (PMID 37366640, 2023). "Next, we investigated if upregulation of Piezo1 channels is also evident in vivo in an aging rat model of Alzheimer’s disease pathology (TgF344-AD)." (PMID 30405400, 2018). "Astrocytic Piezo1 channel activation is related to cognitive functions, and its activation of Piezo1 by transcranial magnetic stimulation was beneficial for slowing cognitive decline in a model of Alzheimer’s disease." (PMID 38612801, 2024). "Piezo1 signaling was also shown to play a role in the pathophysiology of Alzheimer’s disease." (PMID 35722613, 2022). "In addition, it is speculated that in the brain of those with Alzheimer’s disease (AD), astrocytes sense changes in the environment and subsequently relay the information to damaged neurons around the Aβ plaques instead of sensing stimuli via the damaged neurons that lost their PIEZO1 function." (PMID 36765838, 2023). "Additionally, Piezo1‐mediated mechanotransduction plays significant roles in normal aging and brain injury, as well as the development of various brain diseases, including demyelinating diseases, Alzheimer's disease, and brain tumors." (PMID 37366640, 2023).
heart failure (17 papers, 2018 to 2026). Inability of the heart to pump blood at an adequate rate to meet tissue metabolic requirements. "In this study, we aimed to determine the mechanisms of heart failure in carriers of GOF PIEZO1 variants by integrating data from both human and animal studies." (PMID 41237237, 2025). "PIEZO1, a mechanosensitive calcium channel, regulates stretch-induced ROS signaling and is linked to cardiomyopathy and heart failure in mouse and human models 49,50." (PMID 40832351, 2025). "In larger populations, investigating the relationship between PIEZO1 mutations and heart failure is particularly challenging." (PMID 41237237, 2025). "In addition, a small case series reported a 25-year-old patient with HX harboring the PIEZO1 V2006D variant who experienced sudden death, presumably due to myocardial iron overload leading to heart failure." (PMID 41237237, 2025). "Murine studies have demonstrated that cardiac-specific knockout of Piezo1 impairs systolic function of the heart, whereas targeted overexpression of Piezo1 in cardiac tissue leads to severe heart failure and arrhythmias." (PMID 41583526, 2026). "Elevated levels of the PIEZO1 protein have been observed in both humans and mice with heart failure." (PMID 41237237, 2025). "However, the mechanism by which GOF PIEZO1 mutations contribute to heart failure remains unclear." (PMID 41237237, 2025). "In cardiomyocytes, increased PIEZO1-mediated Ca2+ signaling impairs lipid metabolism, ultimately contributing to heart failure." (PMID 41237237, 2025). "This review provides new possible targets for heart failure therapy by exploring the cellular functions of Piezo1 that are involved in the progression of the disease." (PMID 37504285, 2023). "On the other hand, cardiac-specific overexpression of Piezo1 was also related to arrhythmias and heart failure." (PMID 35897650, 2022). "Together, these characterizations demonstrate that cardiac-specific overexpression of Piezo1 leads to severe heart failure and arrhythmias, consistent with abnormal Ca2+ handling and ROS signaling in the Piezo1-TG cardiomyocytes." (PMID 33558521, 2021). "This suggests that Piezo1 may play a pivotal role in ventricular remodeling during the progression of heart failure." (PMID 41583526, 2026). "Increased Piezo1 mRNA and PIEZO1 proteins were detected in rat hearts 4 or 8 weeks after ligation, and at 8 weeks were concomitant with a left ventricular ejection fraction below 50%, indicating potential relevance to heart failure." (PMID 40721314, 2025). "However, under pathological conditions, the aberrant expression or activation of PIEZO1 leads to adverse cardiac remodeling and eventually heart failure." (PMID 39272994, 2024). "Our study demonstrated that Piezo1 is critically involved in arrhythmogenic remodeling after MI through Ca2+ regulation and revealed it as a new potential anti-arrhythmic target in the treatment of MI and heart failure." (PMID 37303604, 2023). "Activated Piezo1 channel by mechanical stretching generates extracellular Ca2+ influx and provokes mechano-chemo-transduction including calcineurin/calpain and reactive oxygen species (ROS) pathway, which eventually leads to cardiomyopathy and heart failure." (PMID 37303604, 2023). "Conversely, cardiomyocyte-specific overexpression of Piezo1 induces severe heart failure and ventricular tachycardia, indicating that PIEZO1 may also be associated with cardiac arrhythmias." (PMID 37047693, 2023). "In addition, Piezo1 is up-regulated in rats with Ang II-induced heart failure, indicating that Piezo1 is also involved in arterial remodeling after injury." (PMID 35154133, 2022). "Such a molecular mechanism might account for the severe heart failure and arrhythmia of the Piezo1-TG mice." (PMID 33558521, 2021). "Previous study revealed that Piezo1 is up-regulated by Angiotensin II in a heart failure rat model." (PMID 30400259, 2018).
heart failure (continued). "Modulation of Piezo1 activity may, therefore, effectively delay the progression of heart failure." (PMID 37504285, 2023). "In the future it will be useful to expand knowledge of how the sensitivity of Piezo1 is set and regulated in various contexts, including in aging, features of which are microvascular apoptosis and exercise intolerance in common diseases of old age such as heart failure." (PMID 35025768, 2022). "Together with the observation that cardiac-specific Piezo1-TG mice displayed severe heart failure, these data collectively demonstrate that maladaptive upregulation of Piezo1 in response to cardiac perturbation might contribute to the pathogenesis of cardiomyopathy in both mouse and human hearts." (PMID 33558521, 2021). "We believe that, based on the preclinical work reported here, Piezo1 could play an important role in cardiac fibroblasts biology and offers a unique opportunity to modify the maladaptive cardiac remodeling in response to injury, ultimately leading to heart failure." (PMID 35897650, 2022). "Additionally, Piezo1 expression is elevated in cases of heart failure, and the binding of AngII to the AngII type 1 receptor (AT1) mediates the Erk1/2 pathway, enhancing the activity of the Piezo1 channel." (PMID 41583526, 2026). "In addition to these classical pathways, studies have found that Piezo1 interacts with the Hippo-YAP/TAZ pathway, enhancing fibrosis and ECM deposition, ultimately accelerating myocardial remodeling and the onset of heart failure." (PMID 41195420, 2025). "Our observation that Piezo1 is decreased compared to control in the 5% and 25% stretch suggests that the stretched cardiomyocytes were not that of heart failure condition, and Piezo1 decrease may be acting to counteract cardiomyopathy." (PMID 30400259, 2018).